ENSG00000272410 (novel protein)
Gene: Protein-coding gene on chromosome 3 (10,249,372 to 10,285,796, forward strand). Ensembl gene ENSG00000272410.
Genetic constraint (gnomAD): Missense variants: 847 observed, 849.47 expected, observed/expected ratio (o/e) 1, 90% interval 0.94 to 1.05. Synonymous variants: 338 observed, 316.61 expected, observed/expected ratio (o/e) 1.07, 90% interval 0.98 to 1.17.